TNF (tumor necrosis factor)
Diseases named in the same sentence as TNF in open-access papers (continued):
Sharing a sentence is not in itself a finding about the gene and the disease.
leprosy (continued). "Other reports also document a range of TNF values and a lack of correlation with clinical outcome in leprosy patients." (PMID 21408123, 2011). "We mined an independent leprosy single-cell RNA-Seq (scRNA-Seq) dataset composed of RR and L-lep skin lesions (GSE151528) and found that IL1B mRNA expression in RR lesions was restricted to myeloid cells, while TNF was expressed by both myeloid and T cells, with higher expression in myeloid cells." (PMID 40569678, 2025). "Adalimumab, a tumor necrosis factor-alpha inhibitor, is not a treatment for BT leprosy." (PMID 38716298, 2024). "Here, we evaluated serum levels of both TNF and IL-6 in leprosy patients with or without CB." (PMID 34797866, 2021). "Furthermore, stimulation of PBMC isolated from ENL patients with TLR9 agonist led to higher levels of TNF-α, IL-6, and IL-1β, than those of non-reactional leprosy and healthy controls." (PMID 28348555, 2017). "We have additionally investigated the classic candidate genes TNF/LTA, IFNG, and IL10, which were consistently associated with leprosy per se but, despite the central roles of these cytokines in leprosy reactions, were not genetically associated with reaction outcomes in our study." (PMID 28715406, 2017). "Additionally, we found that there were no reports on the in vitro effect of steroids on TNF-α production in short term cell culture in leprosy patients and therefore carried out an in vitro study." (PMID 25070345, 2014). "Raised serum TNFα levels have been reported in Erythema Nodosum Leprosum (ENL) reactions and one could hypothesise that TNFα might leak from sites of inflammation into the circulation and so be a marker of acute leprosy related inflammation." (PMID 21408123, 2011). "Indeed, the increase in TNF, IL-1β, IL-6, MCP-1, and MIP-1β mediators typically produced by monocytes supports the idea of BCG-induced “trained immunity” as a Th1/Th17 heterologous mediating mechanism of immune activation favoring disease protection of HC of leprosy patients." (PMID 28467415, 2017). "Among the articles of leprosy reactions, regardless of the type of sample, IFN-γ, TNF-α, IL-6, and IL-1β were involved in T1Rs and T2Rs." (PMID 26339136, 2015). "In this systematic review, we identified important pro- and anti-inflammatory mediators involved in the occurrence of dental infections and leprosy reactions, including IL-6, IFN-γ, TNF-α, IL-1β, IL-17, IL-10, and IL-4, which were independent of the laboratory technique and sample." (PMID 26339136, 2015).
insomnia (83 papers, 2017 to 2025). A sleep disorder characterized by difficulty in falling asleep and/or remaining asleep. "To examine the inflammatory profile associated with insomnia, we evaluated serum TNF-α and IL-1 concentrations." (PMID 40851868, 2025). "(II) The search strategy incorporates multiple synonyms and MeSH terms related to sleep quality, insomnia, sleep disturbances, IL-6, TNF-α, and exercise, thereby reducing the risk of missing relevant studies." (PMID 40729041, 2025). "Certain cytokine-associated substances, including TNF and IL-1 soluble receptors, can function as antagonists, inhibiting spontaneous sleep and causing symptoms such as insomnia or excessive daytime sleepiness." (PMID 38755574, 2024). "Key findings indicate that inadequate sleep and sleep disorders, such as insomnia and obstructive sleep apnea, are associated with elevated levels of pro-inflammatory cytokines like IL-6 and TNF-α, which can impair immune surveillance and promote tumor growth." (PMID 39120277, 2024). "Insomnia means less sleep, which causes the body to produce more interleukin 6 and tumor necrosis factor, and also activates STAT family proteins." (PMID 37334291, 2023). "Chronic inflammation and oxidative stress are closely linked to insomnia, and Tai Chi can attenuate systemic inflammation by decreasing pro-inflammatory cytokines (e.g., IL-6, TNF-α) and increasing anti-inflammatory cytokines (e.g., IL-10), while enhancing antioxidant defenses." (PMID 41280447, 2025). "Insomnia and sleep deprivation are known to be associated with a low-grade pro-inflammatory state, characterized by the release of acute-phase proteins and cytokines, including IL-1, IL-6, and TNF-α." (PMID 36062000, 2022). "Both preclinical and clinical investigations have consistently observed elevated peripheral blood levels of IL-6, IL-1β, and TNF-α in insomnia patients." (PMID 41310834, 2025). "Conversely, outcomes such as waist circumference, CRP, IL-6, TNF-α, QoL (quality of life), fatigue, pain, insomnia, physical functioning, and emotional functioning were rated as moderate quality due to small sample sizes." (PMID 40642165, 2025). "Disruption of these rhythms—through insomnia, irregular schedules, or shift work—can impair vaccine responses by blunting the release of key cytokines like TNF-α and IFN-γ." (PMID 40872930, 2025). "One viewpoint suggests that elevated levels of pro-inflammatory cytokines can worsen insomnia, while exercise can help restore a stable sleep–wake cycle by improving TNF-α, IL-1β, IL-6, and other pro-inflammatory cytokines." (PMID 40115345, 2025). "Acupuncture elevates plasma TNF-α in insomnia-model rats, potentially improving sleep quality through this mechanism." (PMID 41161257, 2025). "The selected manuscripts were fully reviewed, and data were extracted to evaluate the effects of exercise protocols on sleep quality, insomnia, and inflammatory markers, specifically IL-6 and TNF-α." (PMID 40729041, 2025). "In an animal model of insomnia rats, acupuncture was found to stimulate the production of IL-1β and TNF-α while maintaining cytokine balance, thus bolstering the immune system and ameliorating insomnia symptoms." (PMID 40371085, 2025). "Our experimental results align with previous studies, concentrations of IL-1β and TNF-α showed marked elevation in insomnia-model rodents compared to healthy controls." (PMID 41409981, 2025). "This study was conducted as a systematic review and meta-analysis aimed at evaluating and quantifying the effects of aerobic and anaerobic exercise on sleep quality, insomnia, and inflammatory markers (IL-6 and TNF-α)." (PMID 40729041, 2025). "Previous studies have demonstrated that insomnia patients exhibit elevated levels of IL-6, IL-10, IL-1β, TNF-α, CRP, and other inflammatory markers." (PMID 40636389, 2025). "Both IL-1 beta and TNFα modulate sleep and the sleep–wake cycle, and low levels of these cytokines are related to insomnia." (PMID 39585035, 2024).
insomnia (continued). "Nevertheless, we found a significant association between greater sleep fragmentation and IL-6, decreased SWS and TNF-α, and greater insomnia severity, sleep duration, and CRP." (PMID 37081449, 2023). "IL-6, IL-1β, and TNF-α are common inflammatory factors, and significantly higher IL-6 and TNF-α levels are reported in patients with insomnia than in healthy individuals, whereas decreasing their levels had a calming effect." (PMID 37670944, 2023). "The levels of melatonin, TNFα, and IL-6 were correlated with the Insomnia Severity Index so that the higher the insomnia score, the higher the levels of TNF-α and IL-6 and the lower the melatonin levels." (PMID 33579032, 2021). "Insomnia is, in fact, associated with marked decreases in the numbers of T-cells and high levels of CRP and of both IL-6 and TNF." (PMID 35444704, 2021). "Participants with improved insomnia also demonstrated attenuated IL-6 and TNF-α responses to an evoked laboratory pain challenge." (PMID 36776493, 2020). "Inflammation markers such as CRP,TNF-α, and IL-6 may represent a common physiological process linkingshorter sleep duration and insomnia to mortality." (PMID 39867194, 2025). "This study will focus on key serum biochemical markers, including neurotransmitters (5-HT and GABA), inflammatory cytokines (IL-1β, IL-6, TNF-α), and endocrine hormones (melatonin and hormones related to the HPA axis), as these have been implicated in the pathophysiology of insomnia." (PMID 40371071, 2025). "Moreover, insomnia also activates the inflammatory cascade with a secretion increase in the C-reactive protein, IL-6, and TNFα." (PMID 39585035, 2024). "When sleep deprivation occurs, IL-6 and TNF-α increase in the body, and when the body shows high levels of inflammation, it leads to a decrease in sleep duration and induces split sleep, which leads to sleep disturbances such as insomnia." (PMID 38502408, 2024). "The substantial enrichment of the TNF signaling pathway and the IL-17 signaling pathway suggests that sleep cocktail may play a role in the treatment of insomnia through these two pathways, and both pathways are related to the inflammatory response." (PMID 38927034, 2024). "In addition, treatment of sleep disorders such as insomnia can reverse the levels of inflammatory markers and reduce IL-6 and TNF levels to alleviate systemic inflammatory responses." (PMID 37872570, 2023). "Previous studies have reported associations of insomnia and sleep disturbances with elevated levels of inflammatory biomarkers, including several biomarkers considered in our analyses such as CRP, IL-6 and TNF-α." (PMID 36104003, 2022). "Moreover, we found that IL-1β levels were significantly higher in insomnia patients while TNF-α was significantly reduced." (PMID 36190400, 2022). "Similarly, it has been suggested, in a sample of nurses with clinical insomnia working shifts, that Shimian Granules increased sleep quality by enhancing in opposite directions the salivary levels of melatonin and TNF-α." (PMID 33579032, 2021). "Moreover, the evidence suggests that individuals with insomnia had increased pro-inflammatory cytokines such as IL-6, nuclear factor-κB, and TNF-α." (PMID 31404954, 2019). "Therefore, this study aimed to examine the effect of Lactobacillus (Lactiplantibacillus) plantarum P72, isolated as a strain suppressing lipopolysaccharide-induced expression of TNF-α in Caco2 cells, on DA and insomnia in immobilization stress (IS)- or cultured fecal microbiota (cFM)-treated mice." (PMID 39519543, 2024). "Our analysis shows that ZSS can effectively act on multiple targets such as TNF and IL-2 simultaneously through various components such as swertisin, jujuboside A, and spinosin, which makes the drug molecules affect the protein, and this achieves the effect of treating insomnia." (PMID 34745308, 2021).
insomnia (continued). "A number of cytokines and chemokines, including interleukin-1 beta (IL-1β), tumor necrosis factor-alpha (TNF-α) and IL-6, as well as high-sensitivity C-reactive protein (hs-CRP) have been shown to be related to insomnia." (PMID 28060925, 2017). "From a pathophysiological standpoint, insomnia activates the hypothalamic-pituitary-adrenal (HPA) axis and disrupts circadian cortisol rhythms, thereby increasing systemic inflammation through elevated levels of cytokines such as IL-6 and TNF-α." (PMID 40756597, 2025). "Recent studies provide laboratory based evidence that acupuncture affects the sleep-wake-up cycle by interfering with many levels of insomnia-related cytokines and neurotransmitters (such as 5-HT, NE, DA, GABA, Glu, IL-1, IL-6, TNF, and NO) which plays a role in sedative hypnosis and promotes sleep." (PMID 31341495, 2019). "The potential correlation between the BDNF levels, interleukin-6 (IL-6), tumour necrosis factor-alpha (TNF-α), and depressive symptoms such as nine-item patient health questionnaire (PHQ-9) and Athens insomnia scale (AIS) were evaluated with multivariate logistic regression analysis." (PMID 31234814, 2019). "Furthermore, it has been found that variability of bedtime and wake time is associated with a high level of the inflammatory biomarker called tumor necrosis factor (TNF)-alpha in people with and without insomnia." (PMID 31855189, 2019). "The insomnia-mediated insulin resistance and metabolic syndrome could be correlated with the progression of NAFLD, possibly due to increased secretion of inflammatory cytokines such as IL-6 and TNF-α, leading to an abnormal increase in hepatic free fatty acids owing to adipocyte lipolysis." (PMID 37163444, 2023).
brain inflammation (82 papers, 2006 to 2025). "The production of large amounts of TNF-α and IL-6 in immune cells is an important factor in causing acute brain inflammation." (PMID 39860162, 2025). "Results revealed that ZIKV caused brain inflammation and that elevated TNF-α led to microglial activation and phagocytosis of hippocampal synapses in mice." (PMID 31488835, 2019). "In addition, neuronal loss and microglial activation brought on by LPS-induced brain inflammation caused the release of neurotoxic substances, including inflammatory cytokines (TNF-α and IL-6)." (PMID 36986497, 2023). "Furthermore, LPS-induced brain inflammation is accompanied by neuronal loss and microglia activation, which induce the release of neurotoxic factors, such as inflammatory cytokines (TNF-α, IL-1β, PGE2, etc.)." (PMID 30962497, 2019). "Pro-inflammatory cytokine levels (IL-1β, IL-6, and TNF-α) in the hippocampus were measured via ELISA to assess brain inflammation in mice." (PMID 41155481, 2025). "The direct effect of the activated p38 kinase pathway is the deregulation of inflammation (e.g., reduced levels of TNF-α, IL-1, IL-6, and IL-8) maintaining prolonged brain inflammation." (PMID 40171450, 2025). "The current study discovered that diabetic animals with LPS-induced brain inflammation had higher concentrations of TNF-α and IL-6." (PMID 38753370, 2024). "Recent articles indicate that the intrathecal pre-treatment of RvE1 prohibits the induction of nerve injury-induced nociception and increases in Iba-1 (microglial marker) and TNF-α (brain inflammation) in mice spinal cords." (PMID 38474148, 2024). "Tumor necrosis factor-α (TNF-α) is an inflammatory factor that is secreted by microglia in response to brain inflammation." (PMID 38255315, 2024). "Two key mediators of these inflammatory effects are IκB kinase β (IKKβ) and tumor necrosis factor-α (TNF-α), which are pro-inflammatory cytokines that have been shown to actively contribute to brain inflammation." (PMID 38398503, 2024). "It is possible that here the LDL-mediated increase in brain citrate protected against LPS-induced brain inflammation, resulting in the reduced levels of brain IL-β and TNF observed, though further experiments are needed to clarify this." (PMID 37095493, 2023). "To evaluate brain inflammation, we examined the expression of TNF-α and the activation of allograft inflammatory factor 1 (Iba1)." (PMID 37950725, 2023). "Despite the previously reported expression of MC1R in a human astrocyte cell line and suggested glial cell MC1R-mediated inhibition of TNF-α by α-MSH in a mouse model of brain inflammation, our double-labeling showed rare colocalization of MC1R and GFAP." (PMID 35197079, 2022). "Here we report that GSTM1 significantly affects TNF-α-dependent transcriptional program in astrocytes and modulates neuronal activities and stress during brain inflammation." (PMID 36685285, 2022). "TNF-α, IL-1β, and IL-6 are involved in the progression of brain inflammation through inducing the expression of chemokines that facilitate the infiltration of leukocytes into the CNS." (PMID 34765767, 2021). "Several studies reported that in physiological conditions histamine induces both astrocytic and microglia reactivity and increase the release of pro-inflammatory cytokines such as TNFα and IL-6 through H1R and H4R thus sustaining brain inflammation." (PMID 33918940, 2021). "Recent pathophysiology-associated studies showed that BS attenuates rheumatoid inflammation in mice via modulating macrophages, and reduced expression of inflammatory cytokines and TNFα in brain inflammation-induced Wistar rats." (PMID 32854331, 2020). "AD is an inflammatory brain disease with microglia located near the β-amyloid plaques and increased release of tumor necrosis factor-alpha (TNF-α)." (PMID 30641861, 2019). "Brain inflammation activates microglia and leads to the production of proinflammatory molecules such as TNF-α, IL-1β, and IL-6." (PMID 31444225, 2019).
brain inflammation (continued). "Altered IL-1β, IL-6, and TNF-α expression levels activating the STAT3 pathway have been found in brain inflammation models." (PMID 28143489, 2017). "Guy C. Brown found that activation was accompanied by partial rounding up and mobility of the cells, proliferation, and the expression and release of pro-inflammatory cytokines, including TNF-α, IL-1 β, and IL-6 in the event of brain inflammation." (PMID 24236147, 2013). "IL-1β and TNF-a are two main proinflammatory cytokines of microglial source, which represent the level of brain inflammation." (PMID 24289479, 2013). "Compared with WT mice, Tim-3−/− mice had reduced ICH-induced brain inflammation with decreased TNF-α and IL-1β, cerebral edema and neurological deficit scores." (PMID 24289479, 2013). "We demonstrate that DMF inhibits a proinflammatory response characterised by increased microglial and astrocytic synthesis of NO, IL-1, IL-6 and TNF-α in an in vitro model of brain inflammation." (PMID 20482831, 2010). "Brain mast cells can secrete TNF, which is involved in both brain inflammation and blood-brain-barrier (BBB) permeability." (PMID 19825165, 2009). "As a model for brain inflammation, we initially investigated the transcriptional profile of TNF-treated astroglioma cells." (PMID 16987412, 2006). "Brain inflammation is initiated by the activation of microglia and astrocytes, which release proinflammatory cytokines such as interleukin (IL)-1β, tumor necrosis factor (TNF)-α, and IL-6." (PMID 41597301, 2025). "We hypothesize that the mechanism by which miR-4763-3p affects apoptosis is related to brain inflammation; therefore, ELISA, IHC and qPCR were performed to evaluate the expression of the inflammatory factors IL-6 and TNF-α in the mouse brain." (PMID 39664587, 2024). "However, in brain inflammation, activated microglia release much higher TNFα levels, which, via the astrocyte receptor TNFR1, stimulate the production of prostaglandins and massive release of glutamate, altering synaptic function and causing neuronal damage." (PMID 39456170, 2024). "To evaluate brain inflammation, we examined TNF-α expression and Iba1 activation." (PMID 37950725, 2023). "Alcoholism can be considered an inflammatory condition, as peripheral endotoxemia may lead to brain inflammation and increased secretion of pro-inflammatory cytokines such as tumor necrosis factor-alpha (TNF-α), interleukin (IL)-1β, IL-6, and interferon γ." (PMID 35883865, 2022). "Cardiac I/R injury caused brain inflammation as indicated by an increased p-nuclear factor-κB (NF-κB)/NF-κB ratio, while TNF-α protein levels were not affected by cardiac I/R injury, when compared with the sham group." (PMID 34689160, 2021). "Thus, the results indicate the neuroprotective effect of chondroitin sulfate as an anti-inflammatory agent by suppressing the NF-kB and decreasing the inflammatory mediators (IL-1β, IL-6, and TNF-alpha) that act as biomarkers of brain inflammation." (PMID 34833865, 2021). "It is known that TNF-α has a pivotal role in various types of inflammatory brain diseases." (PMID 32867364, 2020). "Microglia is a potential producer of TNF-α during brain inflammation." (PMID 32101593, 2020). "We have shown that P. gingivalis periodontal infection may induce an age-dependent brain inflammation, which increases the TNF- α, IL-6, and IL-1 β levels in middle -aged mice." (PMID 29422938, 2018). "LPS-induced brain inflammation resulted in activated microglial cells and enhanced levels of molecular markers of inflammation such as NFκB signaling pathway and its proinflammatory target proteins (TNF-α and COX-2)." (PMID 24904290, 2014). "This study generates important data elucidating the role of TNF-α in neurogenesis and may provide insight into new therapeutic strategies for brain inflammation." (PMID 23236394, 2012).